MTOR (mechanistic target of rapamycin kinase)
Diseases named in the same sentence as MTOR in open-access papers (continued):
Sharing a sentence is not in itself a finding about the gene and the disease.
viral infection (continued). "To determine the importance of mTOR in RLR-mediated antiviral responses of other DC subsets next we focused our interest on pDCs, which are best known for their ability to produce large amounts of type IFNs as well as various pro-inflammatory cytokines in response to a viral infection." (PMID 33013932, 2020). "In our infection model mTOR inhibitors rapamycin and Torin-1 failed to block viral infection." (PMID 32691695, 2020). "Knockdown of Rae1, mTor, Nup88 or Nup214 did not restore VP2 expression under mutant CrPV(R146A) virus infection compared to wild-type infection, similar to that observed in the control dsRNA treated cells." (PMID 36455064, 2022). "With further research, we found that the protein expression of p-mTOR and its downstream p-p70 S6K and p-4E-BP1 significantly increased with MHY1485 pretreatment, while RAPA inhibited the p-mTOR, p-p70 S6K and p-4E-BP1 protein expressions regardless of the presence or absence of viral infection." (PMID 34367129, 2021). "The lack of Akt/mTOR activation measured here may reflect the longer-term impact of PGC-1α, PGC-1β, and VP16-ERRα overexpression as endpoint measurements were made 72 h post-viral infection." (PMID 30356878, 2018).
thyroid cancer (152 papers, 2012 to 2026). "Mutations in PI3K/AKT/mTOR pathway were reported frequently in advanced thyroid cancers (PDTC or ATC) especially in metastatic or recurrent cases, and also in follicular thyroid carcinomas." (PMID 34831001, 2021). "mTOR inhibitors (mTOR-Is) act on the primary pathogenic pathway of thyroid carcinoma and could exert protective effects." (PMID 40600030, 2025). "Importantly, PI3K/AKT/mTOR signaling is also associated with decreased iodide uptake in thyroid cancer cells." (PMID 34650915, 2021). "In addition, PI3K/AKT/mTOR signaling activation has been shown to be associated with the dedifferentiated phenotype of thyroid cancer, but the mechanism remains elusive." (PMID 34650915, 2021). "Signaling through mTOR and somatostatin pathway is implicated in thyroid cancer development." (PMID 30807575, 2019). "Inhibition of mTOR signaling with rapamycin in combination with inhibition of the driver mutated kinase BRAFV600E with vemurafenib in thyroid cancer may result in more profound anti-proliferative effects." (PMID 26284586, 2015). "Interestingly, p27 was previously noted to have an inverse association with the activity of the PI3K/mTOR pathway in thyroid cancer cells, and repression of this pathway increases p27." (PMID 23077520, 2012). "The mTOR signaling pathway regulates many major cellular processes, is associated with a growing number of pathological conditions, including cancer, and could be a therapeutic target for thyroid cancer." (PMID 40265010, 2025). "For example, membrane-associated ring–CH–type finger 6 (MARCH6) destabilizes DHX9 and activates the AKT (protein kinase B)/mTOR (mammalian target of rapamycin) signaling pathway in thyroid cancer." (PMID 40290118, 2025). "To elucidate the molecular mechanisms underlying bavachinin’s effects, we analyzed the PI3K/AKT/mTOR and MAPK/ERK pathways, both central to thyroid cancer progression." (PMID 41477125, 2025). "Mutations in the PI3K/AKT/mTOR pathway, including PIK3CA, AKT1 and PTEN are infrequent in thyroid cancer, though they can act as early driver mutations in certain RAS-like subtypes." (PMID 39926346, 2025). "Sustained proliferative signaling is a main hallmark of thyroid cancer, due to chronic activation of the main pathways responding to external stimuli, such as MAPK and PI3K/AKT/mTOR." (PMID 41154428, 2025). "Phase 2 clinical trials have, in fact, demonstrated that oncological treatment with mTOR-Is has permitted disease stability in ~65%−76% of patients with thyroid carcinoma of different histology." (PMID 40600030, 2025). "For example, knocking down LPAR5 can inhibit thyroid cancer through the PI3K/Akt/mTOR signaling pathway." (PMID 39671369, 2024). "Given the crucial role of the PI3K/Akt/mTOR pathway in the occurrence and development of thyroid cancer, further investigation of the specific downstream mechanisms by which PPP4R3A regulates the activity of this axis is of great significance." (PMID 38275415, 2024). "In previous clinical trials, mTOR inhibitors have demonstrated the ability to maintain stable disease (SD) in 65% to 74% for advanced thyroid cancer patients, including those with PDTC." (PMID 38356955, 2024). "Thyroid cancer patients with alterations in the PI3K/mTOR/Akt appeared to benefit most from mTOR inhibitors." (PMID 38356955, 2024). "Silencing MAZ and TBK1 alone significantly inhibited the PI3K/Akt/mTOR pathway in thyroid cancer cells, whereas cotransfection with MAZ siRNA and TBK1 siRNA did not strengthen the inhibitory effect of MAZ RNA or TBK1 siRNA on the PI3K/Akt/mTOR pathway." (PMID 36988258, 2023). "Increased AMPK activation, inhibition of AKT/mTOR, and suppressed cyclin levels were also discovered in thyroid cancer cells treated with canagliflozin." (PMID 37509506, 2023). "The signaling pathway known as PI3K/AKT/mTOR plays a role in promoting the proliferation of thyroid cancer cells and contributes to their survival and angiogenesis processes." (PMID 37446316, 2023).
thyroid cancer (continued). "The current study further explored the relationship between Rab22a and PI3K/AKT/mTOR signaling pathway to verify the influence of Rab22a on the malignant progression of thyroid cancer cells, which was unprecedented." (PMID 35757470, 2022). "CBS can regulate the proliferation, migration, and invasion of human thyroid cancer cells via ROS-mediated PI3K/AKT/mTOR and Wnt/β-catenin pathways." (PMID 35795862, 2022). "Altogether, these results suggest that Rab22a can enhance the malignant biological behavior of thyroid cancer cells by activating the PI3K/AKT/mTOR signaling pathway." (PMID 35757470, 2022). "Functionally a LAT1 inhibitor JPH203 or LAT1 KD by siRNA inhibits cell/tumor proliferation via mTOR in several thyroid cancer cell lines (8505C and OCUT-2/6) and in BRAFV600E;PIK3-CAH1047R and 8505C tumors." (PMID 36557253, 2022). "The combination of somatostatin analogue octreotide and mTOR inhibitor everolimus led to greater efficacy in preclinical models of thyroid cancer and clinically in pancreatic neuroendocrine tumors." (PMID 35681620, 2022). "Recent studies have demonstrated that SQSTM1 promotes cell growth and induces autophagy in thyroid cancer by modulating AKT/mTOR signaling pathway." (PMID 35711939, 2022). "Our data together indicate that CBS modulates ROS-mediated PI3K/AKT/mTOR and Wnt/β-Catenin pathways in human thyroid carcinoma cells." (PMID 35795862, 2022). "miR-153 is involved in inhibiting proliferation and development of thyroid carcinoma by targeting RPS6KB1 in the mTOR-dependent pathway." (PMID 36158686, 2022). "Hyperactivation of the PI3K/AKT/mTOR signaling pathway is proved to contribute to the development of various cancers, including thyroid carcinoma." (PMID 35720005, 2022). "We found that CBS can mediate the cell cycle, proliferation, migration, and invasion of human thyroid carcinoma cells via ROS-mediated PI3K/AKT/mTOR and Wnt/β-Catenin signaling pathways." (PMID 35795862, 2022). "ANP32E contributes to the proliferation and migration of thyroid carcinoma cells by enhancing glycolysis mediated by AKT/mTOR/hk2." (PMID 35280441, 2022). "Overall, these data suggest that CBS modulates ROS-mediated PI3K/AKT/mTOR and Wnt/β-Catenin pathways in human thyroid carcinoma cells." (PMID 35795862, 2022). "Earlier research on mechanisms has shown that MAPK/ERK and PI3K/AKT/mTOR cascades functioned as regulatory effects in the development and pathogenesis of thyroid cancer." (PMID 35433709, 2021). "Recent data reported that autophagy can be regulated through the AKT/AMPK/mTOR pathway.Thus, we verified if p62 triggers autophagy in thyroid cancer through this pathway, analysing the expression of related proteins." (PMID 33937040, 2021). "Taken together, our findings indicate that the effects of SS on thyroid cancer cells were mediated by the AKT/mTOR/4E-BP3 axis in a ROS-dependent manner." (PMID 34094961, 2021). "In summary, our results demonstrate the noncanonical activation of TSH-TSHR signaling and its role in increasing the cell mobility and dedifferentiation of thyroid cancer through crosstalk with PI3K/AKT/mTOR signaling." (PMID 34650915, 2021). "Further, the concurrent activation of PKA and mTOR that was observed in human FTCs led to the conclusion that PKA activates mTOR/p70S6K that results in thyroid cancer, indicating that PKA is a vital component regulating FTC in both mice and humans." (PMID 34359735, 2021). "In human thyroid cancer cells, metformin inhibited cell growth, migration, and epithelial-to-mesenchymal transition through inhibiting the mTOR pathway." (PMID 34812264, 2021). "Inhibition of EMT by inhibiting RTK and Akt/mTOR signaling pathways and promoting the expression of E-cadherin in thyroid cancer cells." (PMID 34930256, 2021). "It has been clarified that MAPK/ERK and PI3K/AKT/mTOR cascades robustly participate in the tumorigenesis and development of thyroid cancer." (PMID 35433709, 2021).
thyroid cancer (continued). "Taken together, our results confirm that MARCH6 promotes the growth and migration of thyroid cancer cells via activation of the AKT/mTOR pathway." (PMID 34512155, 2021). "All these data clearly demonstrate that V600EBRAF regulates AMPK and mTOR activities in thyroid cancer cells." (PMID 34204950, 2021). "Our study demonstrated that ENO1 was an oncogene in thyroid carcinoma that acted downstream of mTOR/HIF1α and accelerated thyroid carcinoma progression via regulating CST1." (PMID 33968941, 2021). "Everolimus is a Sirolimus-derived mTOR inhibitor, whose activity against several thyroid cancer cell lines has been confirmed both in vitro and in vivo." (PMID 33292371, 2020). "LPAR3 was reported as a part of the ZEB1-AS1/miR-133a-3p/LPAR3/EGFR axis that promotes thyroid cancer progression by regulating PI3K/Akt/mTOR signaling." (PMID 32724813, 2020). "Constitutive activation of the phosphatidylinositol-3-kinase (PI3K)/AKT/mTOR pathway has been reported in thyroid cancer pathogenesis." (PMID 33292371, 2020). "Using western blot analysis, we first examined thyroid cancer cells response to NVP-BEZ235 by checking the PI3K/Akt/mTOR pathway activity." (PMID 32025215, 2020). "NVP-BEZ235 is a novel dual PI3K/mTOR inhibitor, currently in phase 1/2 clinical trials, exhibiting clinical efficiency in treatment of numerous malignancies including thyroid cancer." (PMID 32025215, 2020). "Studies have shown that thyroid cancer promotes the growth and invasion of cancer cells through the mTOR pathway and MYC45." (PMID 32251318, 2020). "In the present study, cells treated with aloperine exhibited autophagy induction through Akt/mTOR pathway suppression in human thyroid cancer cells." (PMID 31731481, 2019). "Some clinical trials have evaluated the mTOR inhibitor everolimus and the combination of sorafenib and the mTOR inhibitor temsirolimus in the treatment of RAI-R thyroid cancer." (PMID 31533238, 2019). "Taken together, our studies suggest that upregulation of miR-96-3p promotes tumor invasion and metastasis of thyroid cancer via regulating the SDHB/AKT/mTOR pathway." (PMID 31749660, 2019). "Studies have shown that activation of AMPK but inhibition of mTOR inducing autophagy has been regarded as an important mechanism for thyroid cancer therapy." (PMID 31331356, 2019). "We evaluated everolimus, an mTOR inhibitor and pasireotide, a multi receptor somatostatin analogue as potential therapy of thyroid cancer focusing on the in vitro and in vivo efficacy, as well as possible mechanism to explain any observed interaction." (PMID 30807575, 2019). "To date, several trials have employed mTOR inhibitors in thyroid cancer, whereas the phase II MATCH studies are testing PI3K (e.g., taselisib, copanlisib) and AKT-inhibitors (e.g., capivasertib)." (PMID 31540307, 2019). "Acting as a critical regulator of autophagy-mediated NIS degradation via ROS/AMPK/mTOR pathway, HMGB1is a potential intervention target of radioiodine therapy in thyroid cancer." (PMID 31331356, 2019). "The results indicate that exogenous H2S regulates the growth of human thyroid carcinoma cells through the ROS/PI3K/AKT/mTOR signaling pathway." (PMID 31223424, 2019). "In conclusion, our results demonstrate that exogenous H2S regulates the growth of human thyroid carcinoma cells through ROS/PI3K/Akt/mTOR and RAS/RAF/MEK/ERK signaling pathways." (PMID 31223424, 2019). "Suppression of Akt/mTOR pathway was also reported to alter autophagy activation in human thyroid cancer cells." (PMID 29363886, 2018). "Given observed clinical benefits of these drugs, and the belief that mTOR activation is a therapeutic target in thyroid cancer, these agents are being tested in the setting of advanced thyroid cancer." (PMID 29455653, 2018).
thyroid cancer (continued). "To determine the effect of compounds on the proliferation of thyroid cancer cells, we measured the expression and activation level of the genes related to the mTOR pathway in TT cells given intervention with different compounds." (PMID 29498706, 2018). "In thyroid carcinoma, the regulation of translation initiation factor eIF2, mTOR pathway and IMPACT were found to be functionally related to each other." (PMID 30466445, 2018). "A similar pattern emerges in prostate adenocarcinoma, although the clustering of IMPACT with the mTOR pathway is more distant compared to that in thyroid carcinoma." (PMID 30466445, 2018). "RAS/RAF/ERK and PI3K/AKT/mTOR signaling pathways are pivotal for the survival and growth of thyroid cancer cells." (PMID 28476040, 2017). "In this study, ganetespib inhibited RAS/RAF/ERK and PI3K/AKT/mTOR signaling in four histologic types of thyroid cancer cell lines and decreased RET level in a MTC cell line." (PMID 28476040, 2017). "Future studies will investigate the role Src plays in promoting activation of the AKT/mTOR pathway, and how activation of Src increases thyroid cancer signaling plasticity." (PMID 29262541, 2017). "Effects on mTOR also varied among thyroid cancer cell lines, as total mTOR expression decreased in response to metformin in BCPAP and increased in 8505c anaplastic cells." (PMID 26284586, 2015). "Everolimus significantly inhibited cell viability in a dose- and time-dependent fashion and diminished phosphorylation of mTOR in a TT thyroid cancer cell line and cultured human MTCs." (PMID 26294908, 2015). "In this study, we investigated the combination of BRAFV600E inhibition and mTOR inhibition in thyroid cancer cells." (PMID 26284586, 2015). "Several targets of mTOR have been found to be deregulated in thyroid cancer, making it an appropriate target for thyroid cancer research." (PMID 29147373, 2014). "Although the interrelationship between AMPK and mTOR is well described in metabolic tissues such as skeletal muscle, liver and adipose tissue, the AMPK ability to inhibit mTOR has still to be demonstrated in thyroid cell physiology and thyroid cancer." (PMID 27919039, 2014). "RAS/RAF/ERK and PI3K/AKT/mTOR signaling pathways are important in thyroid cancer tumorigenesis, progression and survival." (PMID 24155971, 2013). "RAS/RAF/ERK and PI3K/AKT/mTOR signaling transduction are important for the growth and survival of thyroid cancer." (PMID 24155971, 2013). "An appealing feature of Akt/mTOR inhibitors is the possibility of treating advanced thyroid cancer also when resistance to single targeted therapy is conferred by multiple genetic alterations." (PMID 24267151, 2013). "In thyroid carcinomas we also disclosed an association between BRAF mutation and mTOR pathway overactivation." (PMID 23904987, 2013). "Additionally, GLP1R agonist Liraglutide has been shown to inhibit proliferation and migration in thyroid cancer cells via the PI3K/Akt/mTOR pathway." (PMID 40696350, 2025). "SNHG3 and SNHG5 show relatively low expression in thyroid cancer and possess certain inhibitory effects, closely linked to their roles in autophagy regulation (the SNHG5–RBM47/USP21–FOXO3 axis) and modulation of AKT/mTOR/MAPK signaling pathways." (PMID 41234719, 2025). "These anticancer effects are thought to be mediated through interference with insulin/IGF signalling and modulation of the AMPK/mTOR pathway, which inhibits unchecked cell cycle progression, induces apoptosis in thyroid cancer cells, and reduces colony formation and migration." (PMID 40055991, 2025). "It is thought that IMCA may be a specific antagonist of NR4A1 through the NR4A1 and SESN/AMPK/mTOR signaling pathway and therefore can be used in the treatment of thyroid carcinomas." (PMID 40956676, 2025).